IL27 (interleukin 27)
Diseases named in the same sentence as IL27 in open-access papers (continued):
Sharing a sentence is not in itself a finding about the gene and the disease.
cancer (continued). "We recently reported that IL-27, a heterodimer cytokine related to both IL-6 and IL-12 cytokine families, has several functional activities in common with IFN-γ, in different cancer cells." (PMID 29020964, 2017). "IL-27 induces inhibitory molecules including PD-1, Tim-3, LAG-3, TIGIT, and IL-10, which overlap with the mediators of T cell exhaustion, in chronic viral infections and cancer." (PMID 28545567, 2017). "In a non-cancer model, innate immune receptor agonist-based vaccine adjuvants elicit strong CD8+ T-cell responses that are dependent on IL-2718, illustrating the effect of endogenous IL-27." (PMID 29021521, 2017). "Also, we reported that IL-27, similar to IFN-γ, induces the expression of IL-18BP, IDO and PD-L1 immune regulatory molecules in human cancer cells." (PMID 27683036, 2016). "As EOC cell lines are responsive to IL-27, we asked whether IDO expression may be modulated by IL-27 in a panel of 6 cell lines representative of different sub-types of this cancer." (PMID 26657115, 2015). "Finally, human prostatic PC3 and lung A549 carcinoma cells showed enhanced IDO mRNA and protein expression, in response to IL-27 stimulation (respectively), although induction of IDO protein was in general lower than in EOC cells." (PMID 26657115, 2015). "In the modified model the only source of IL-27 comes from the drug, since cancer cells do not generally secrete IL-27." (PMID 24633175, 2014). "We further described for the first time that IL-27 appeared to distinguish well between tuberculous and non-tuberculous PEs, especially malignant PE." (PMID 22792330, 2012). "IL-27 is known for its broad immunomodulatory functions in inflammation, autoimmunity, and cancer immunity; however, it was not clustered in binding interactions with elevated cytokines in the GD cohort, and its role in GD remains unclear." (PMID 40671914, 2025). "Our data suggest that even immunocompromised or advancer NSCLC patients may benefit from IL-27's antitumor properties based on its ability to drive myeloid cells towards antitumor activities, and down-regulate stemness- and EMT-related genes in cancer cells." (PMID 25638163, 2015).
bacterial infection (23 papers, 2011 to 2024). "Authors also identified IL-27 as a diagnostic biomarker for bacterial infection in critically ill children, which was further validated in independent datasets." (PMID 34680414, 2021). "In consummation, the mechanisms associated with IL-27 blockade upon bacterial infection are associated with increased bacterial killing and therefore decreased bacterial burden within the host cells." (PMID 32802395, 2020). "Because IL-27 protein concentrations can be readily measured in the serum compartment, we tested IL-27 serum protein concentrations as a diagnostic biomarker for bacterial infection in critically ill children." (PMID 23107287, 2012). "Genome-wide expression analysis has provided the foundation for the identification of IL-27 as a novel candidate diagnostic biomarker for predicting bacterial infection in critically ill patients." (PMID 23107287, 2012). "Genome-wide expression analysis has provided the foundation for the identification of IL-27 as a novel candidate diagnostic biomarker for predicting bacterial infection in critically ill children." (PMID 23107287, 2012). "Another possible mechanism by which type I IFN enhances host susceptibility to bacterial infection, relates to the observation that these cytokines stimulate the production of IL-27, a molecule that strongly suppresses IL-17A production." (PMID 21829705, 2011). "Considering the immune-suppressive activity of IL-27, we have hypothesized that elevated IL-27 early in life contributes to enhanced susceptibility to bacterial infection." (PMID 31818960, 2020). "Recent work has shown IL-27 to be a candidate diagnostic biomarker for bacterial infection." (PMID 30475852, 2018). "Our results suggest that IL-27 may serve as a useful biomarker in estimating risk of bacterial infection among critically ill pediatric patients with bloodstream infections." (PMID 26514771, 2015). "Herein we report that interleukin-27 (IL-27) may represent a novel diagnostic biomarker for predicting bacterial infection in critically ill patients." (PMID 23107287, 2012). "IL-27 is a cytokine that exhibits a range pro- and anti-inflammatory properties and thereby acts as a key mediator of bacterial infection-related immune responses." (PMID 37205113, 2023). "Here, we discuss a hypothetical mechanism of how IL-27 regulates immune homeostasis during bacterial infections in a time dependent manner." (PMID 34079555, 2021). "IL-27 is an immune regulatory cytokine that inhibits phagosomal activity of macrophages in response to bacterial infection including Mycobacterium." (PMID 33995365, 2021). "The various studies summarized here clearly indicate the need to better understand the context-dependent functions of IL-27 during bacterial infections." (PMID 34079555, 2021). "When IL-27 signaling is blocked during bacterial infection, a more pro-inflammatory response can be initiated through downregulation of IL-10 and subsequent up-regulation of Th1 cytokines to stop pathogen replication." (PMID 32802395, 2020). "In contrast, IL-27 reduction in vitro through neutralization of IL-27 with a soluble receptor prior to bacterial infection, displayed increased oxidative burst, decreased IL-1β levels and therefore decreased bacterial survival." (PMID 32802395, 2020). "Taken together, we highlight a role for IL-27 in modulating innate immune responses to bacterial infection." (PMID 30209294, 2018). "The AUC’s of the ROC curve to diagnose bacterial infection were 0.62 (0.5–0.68) for IL-27 and 0.65 (0.6–0.73) for PCT." (PMID 30475852, 2018). "Of the class-predictor genes, the Epstein-Barr virus-induced gene 3 (EBI3) subunit of interleukin-27 (IL-27) showed the greatest predictive strength for bacterial infection." (PMID 30475852, 2018). "The primary analysis assessed the accuracy of IL-27 to diagnose bacterial infection in immunocompromised pediatric patients, using PCT as a comparator." (PMID 30475852, 2018).
bacterial infection (continued). "Collectively, these studies demonstrate a role for IL-27 in modulating inflammatory responses that is dependent on the type of bacterial infection model." (PMID 30209294, 2018). "Focusing on the impact of the immunoregulatory cytokine interleukin (IL)-27 on control of innate immune system responses, we examined human immune responses to bacterial products and bacterial infection by E. coli and S. typhimurium." (PMID 30209294, 2018). "IL-27 proved to be quite specific, essentially ruling in a diagnosis of bacterial infection if the level was ≥ 5 ng/mL." (PMID 30475852, 2018). "This exploratory analysis suggests complex interactions between IL-27, PCT, age, and primary diagnosis, and illustrates the challenges associated with estimating the risk of bacterial infection among immunocompromised patients." (PMID 30475852, 2018). "We therefore conducted a follow-up prospective study with the a priori goal of validating the performance of IL-27 as a biomarker to diagnose bacterial infection among hospitalized immunocompromised pediatric patients." (PMID 30475852, 2018). "As a follow-up to prior work implicating IL-27 as a biomarker to diagnose bacterial infection in immunocompromised pediatric patients, we prospectively tested IL-27’s utility among this population, and used a priori criteria for successful validation." (PMID 30475852, 2018). "IL-27 outperformed PCT with an AUC for the ROC curve to diagnose bacterial infection of 0.81 and a positive predictive value of 94%." (PMID 30475852, 2018). "Despite prior work demonstrating IL-27 to be a possible biomarker of bacterial infection in immunocompromised patients, we were unable to validate these findings." (PMID 30475852, 2018). "Interleukin-27 (IL-27) has shown early promise in a recent preliminary study, exhibiting high specificity and positive predictive values for bacterial infection in critically ill children." (PMID 26514771, 2015). "This validation study was performed to assess the value of IL-27 in predicting bacterial infection among patients admitted to the pediatric intensive care unit and to compare its performance with that of PCT." (PMID 26514771, 2015). "Of these 100 predictor genes, EBI3, a subunit of IL-27, was discovered as having the highest predictive strength for bacterial infection." (PMID 26514771, 2015). "In the primary analysis, both IL-27 and PCT demonstrated poor reliability for estimating bacterial infection risk, as determined by a priori criteria based on the previously published ROC curve." (PMID 26514771, 2015). "Findings included a specificity and positive predictive value of more than 90 % for bacterial infection in those with IL-27 levels of at least 5 ng/ml performing significantly better than PCT." (PMID 26514771, 2015). "Collectively, these data indicate that serum IL-27 can potentially serve as an effective "rule-in" test for bacterial infection in critically ill patients." (PMID 23107287, 2012). "At a cut point of ≥5.0 ng/ml, serum IL-27 had a specificity and positive predictive value of >90% for bacterial infection in this cohort of critically ill patients." (PMID 23107287, 2012). "Accordingly, we investigated the ability of serum IL-27 protein concentrations to predict bacterial infection in critically ill patients." (PMID 23107287, 2012). "• Serum IL27 protein concentrations had a high specificity and positive predictive value for predicting bacterial infection in a cohort of critically ill children." (PMID 23107287, 2012). "Collectively, these studies highlight the diverse effects of IL-27 in various bacterial infections." (PMID 36028492, 2022). "IL-27 is a unique cytokine with reported immunostimulatory and immunosuppressive effects on various immune cells, and understanding of its precise role during bacterial infections remains incomplete." (PMID 34079555, 2021).
bacterial infection (continued). "However, further research is needed to understand the exact role of IL-27 in immune response against bacterial infections." (PMID 34079555, 2021). "Specifically, it has been reported that IL-27 receptor expression is upregulated in intestinal epithelial cells during inflammation and bacterial infection, whereby IL-27 promoted enhanced barrier function through increased epithelial cell proliferation and restoration." (PMID 32802395, 2020). "Combination of IL-27 treatment with anti-viral or anti-microbial treatment might further expand the applicability of this concept, especially when the role of IL-27 in secondary bacterial infection is appropriately taken into account." (PMID 24809349, 2014). "Thus, it is biologically plausible that IL-27 can serve as a biomarker of bacterial infection in critically ill patients." (PMID 23107287, 2012). "As IL-27 has paradoxical pro-inflammatory and anti-inflammatory properties, its administration as a therapeutic treatment may be effective depending on the timing of administration, and the progression of the bacterial infections." (PMID 34079555, 2021). "We reasoned that IL-27 treatment may modulate responses to bacterial infection." (PMID 30209294, 2018). "However, type-I IFN induction of IL-27 during bacterial infection has been described." (PMID 27926930, 2016). "Thus, serum IL-27 has the potential to serve as an effective "rule-in" test, given that concentrations ≥5 ng/ml had a >90% specificity and positive predictive value for bacterial infection in this cohort of critically ill patients." (PMID 23107287, 2012). "The results of this study confirmed that IL-27 levels in the serum and liver of mice were elevated after CLP-induced bacterial infection, and IL-27 played an important role in promoting inflammatory injury to the liver after CLP." (PMID 33564275, 2021). "This study assessed the utility of interleukin-27 (IL-27) and procalcitonin (PCT) as biomarkers of bacterial infection among immunocompromised pediatric subjects." (PMID 30475852, 2018). "IL-27, composed of IL-27p28 (p28) and Epstein Barr Virus-induced gene 3 (EBI3) subunits, is produced in response to bacterial infection in myeloid cells and exhibits both pro- and anti-inflammatory functions." (PMID 30209294, 2018). "Despite prior work demonstrating IL-27 and PCT as possible biomarkers of bacterial infection in immunocompromised pediatric patients, we were unable to validate these findings." (PMID 30475852, 2018). "The receiver operating characteristic curves yielded AUC’s of 0.62 (0.5–0.68) for IL-27 and 0.65 (0.6–0.73) for PCT to diagnose bacterial infection." (PMID 30475852, 2018). "Serum IL‐27 was similar to CRP, a known biomarker of bacterial infection, in that levels of this gene product were increased during exacerbations associated with sputum purulence, itself a sign of bacterial involvement in exacerbation." (PMID 24994897, 2014). "Using a large genome-wide expression database of critical children in the pediatric ED, predictor genes coding for the IL-27 protein were described; in particular, EB13, a subunit of IL-27, appeared to have a high predictive role for bacterial infections (more than 90%)." (PMID 38254697, 2024). "Although IL-27 does not affect S. typhimurium internalization, it does enhance cytokine production for a more robust immune response to fight and clear bacterial infection." (PMID 30209294, 2018). "Using the previously determined cutoff of 5.0 ng/mL, the specificity of IL-27 to diagnose bacterial infection reached 94%, with a negative predictive value of 64%." (PMID 30475852, 2018). "Conversely, serum IL-27 protein concentrations <5 ng/ml do not necessarily rule out bacterial infection, given that the negative predictive value for a concentration ≥2 ng/ml was 78%." (PMID 23107287, 2012). "Finally, we have no data regarding the temporal production of IL-27 during the course of bacterial infection." (PMID 23107287, 2012).
bacterial infection (continued). "With a combination of IL-27 and PCT, we were able to demonstrate an improved overall ability to both "rule in" and "rule out" bacterial infection in this cohort of critically ill patients." (PMID 23107287, 2012).
infectious disease (22 papers, 2013 to 2024). A disorder directly resulting from the presence and activity of a microbial, viral, or parasitic agent in humans. "Recently, elevated IL-27 levels were associated to dysfunctional immune response to infectious diseases, potentially leading to significant tissue damage." (PMID 39192975, 2024). "IL-27 is a multifunctional cytokine that can either promote or inhibit T cell responses and is implicated in both autoimmune and infectious diseases." (PMID 34299138, 2021). "Interleukin‐27 (IL‐27) gene polymorphisms are linked to infectious disease susceptibility and IL‐27 plasma level is associated with HIV infection." (PMID 30632263, 2019). "Recent studies revealed that single nucleotide polymorphisms (SNPs) of the IL-27 promoter region modulate the development of infectious diseases and individual's susceptibility to therapeutic response." (PMID 25236666, 2014). "The high levels of IL-27 in neonates coincided with the time period of maximum susceptibility for infectious diseases in childhood underpinning a critical role IL-27 may play." (PMID 26054397, 2015). "The IL-12 family of cytokines consists of IL-12 and IL-23 which are pro-inflammatory, and IL-27 and IL-35 which are immune-suppressive and regulate the immune response in autoimmune and infectious diseases." (PMID 38969968, 2024). "Even though IL-39 shares IL-23p19 with IL-23 and shares EBi3 with IL-27 and IL-35, their roles in human infectious diseases are unclear." (PMID 37215496, 2023). "The pleotropic nature of IL27 has led to conflicting reports regarding its role in the context of infectious diseases." (PMID 32547548, 2020). "Altered expression of IL-27 is shown in autoimmune and infectious disorders, and therapeutic targeting of IL-27 is proposed in several of these." (PMID 29176764, 2017). "Thus, the exact role of IL-27 in the context of infectious diseases remains a topic of debate and active research." (PMID 34079555, 2021). "Thus, an urgent need exists for better understanding the molecular mechanisms of IL-27 in the development of infectious diseases to target IL-27 in a more successful manner." (PMID 34079555, 2021). "As such, harnessing or opposing IL-27 activity may have the potential to treat a variety of infectious diseases." (PMID 32802395, 2020). "These IL-27 levels were gradually risen in line with CAP disease severity, and logistic regression analyses confirmed that higher serum IL-27 concentrations were associated with CAP severity scores, underscoring the close link between this cytokine and the progression of this infectious disease." (PMID 34975300, 2022). "Thus, IL-27 is considered a potent agent for treating infected cells and infectious diseases." (PMID 33525571, 2021).
immune diseases (9 papers, 2012 to 2025). "Recent evidence indicated that interleukin (IL)-27 showed pleiotropic properties in immune diseases." (PMID 36405994, 2022). "IL-27 regulates various immune diseases through its dual proinflammatory and anti-inflammatory effects on immune responses." (PMID 26783266, 2016). "It is well accepted that IL-27 regulates various immune diseases through its dual proinflammatory and anti-inflammatory effects on immune responses." (PMID 22792330, 2012). "Given that both TIM-3 and Gal-9 contribute to T cell exhaustion and immunosuppressive signalling, our findings suggest that IL-27 may enhance these pathways and thereby promote immune dysfunction related to advanced disease." (PMID 41296385, 2025). "EBI3 is also a subunit of anti-inflammatory and immunosuppressive cytokines such as IL-27 and IL-35, which suggest MSCs may play a suppressive role in the onset and progression of immune disorders by secreting EBI3." (PMID 36548354, 2022).
cardiovascular disease (8 papers, 2015 to 2025). "More importantly, in patients with cardiovascular disease, two studies have shown an association between IL-27 levels and unfavorable outcomes." (PMID 41302192, 2025). "This review discusses the current understanding of the role of these recently identified interleukins, such as IL-27, IL-31, IL-32, IL-33, and the IL-28 group (IL-28A, IL-28B, IL-29), in the development of cardiovascular diseases." (PMID 39844544, 2025). "Although further research is needed to elucidate these pathways, the evidence underscores IL-27’s context-dependent effects, as it mediates both pro-inflammatory damage and anti-inflammatory repair processes in cardiovascular diseases." (PMID 39906735, 2024). "IL-27 has a two-sided regulatory effect in cardiovascular disease, with both protective and damaging effects; while IL-35 has been found to play a protective role in all cardiovascular diseases." (PMID 32194399, 2020). "Studies in animal models have shown an atheroprotective role whereas human studies demonstrated an important proatherogenic role of IL27 in cardiovascular disease." (PMID 26663990, 2015). "Serum RBP4, hs-CRP, and IL-27 play an important role in the occurrence and development of CHD, with a positive correlation to the Gensini score, which can indicate the severity of cardiovascular disease to a certain extent." (PMID 34956579, 2021).